GALNT16 (polypeptide N-acetylgalactosaminyltransferase 16)
Description:
Catalyzes the initial reaction in O-linked oligosaccharide biosynthesis, the transfer of an N-acetyl-D-galactosamine residue to a serine or threonine residue on the protein receptor.
Synonyms: GalNAc-T16; GALNTL1; KIAA1130; GALNACT16
Tractability: Antibody: UniProt predicts a signal peptide or a membrane-spanning region. PROTAC: ubiquitination databases record sites on it; its protein half-life has been measured.
Gene: Protein-coding gene on chromosome 14 (69,259,277 to 69,357,033, forward strand). Ensembl gene ENSG00000100626.
Subcellular location: Golgi apparatus membrane
Subcellular location (Human Protein Atlas): Cytosol; Vesicles
Pathways (Reactome):
Metabolism of proteins: O-linked glycosylation of mucins
Gene Ontology:
Molecular function: polypeptide N-acetylgalactosaminyltransferase activity
Biological process: protein O-linked glycosylation via N-acetyl-galactosamine; protein O-linked glycosylation
Cellular component: Golgi apparatus; Golgi membrane
Genetic constraint (gnomAD): Loss-of-function variants: 19 observed, 47.85 expected, observed/expected ratio (o/e) 0.4, 90% interval 0.28 to 0.58. The upper end of that interval is the gene's LOEUF score, 0.58, which puts it in group 2 of 6, group 1 being the genes least tolerant of losing a copy. Missense variants: 450 observed, 550.52 expected, observed/expected ratio (o/e) 0.82, 90% interval 0.76 to 0.88. Synonymous variants: 202 observed, 223.05 expected, observed/expected ratio (o/e) 0.91, 90% interval 0.81 to 1.02.
Homologues: Orthologues: chimpanzee GALNT16 (99% identical), mouse Galnt16 (96% identical), rat Galnt16 (96% identical), guinea pig GALNT16 (94% identical), pig GALNT16 (94% identical), dog GALNT16 (94% identical), macaque GALNT16 (87% identical), rabbit GALNT16 (86% identical), tropical clawed frog galnt16 (73% identical), zebrafish galnt16 (67% identical), Caenorhabditis elegans gly-5 (38% identical), Drosophila melanogaster Pgant9 (37% identical), and 11 more. Paralogues in human: GALNT14 (53% identical), GALNT2 (51% identical), GALNT6 (40% identical), GALNT3 (39% identical), GALNT10 (38% identical), GALNT11 (38% identical), GALNT4 (37% identical), GALNT13 (37% identical), GALNT12 (37% identical), GALNT5 (37% identical), GALNT1 (36% identical), GALNTL6 (36% identical), and 7 more.
Diseases named in the same sentence as GALNT16 in open-access papers:
GALNT16 is named in the same sentence as 18 diseases in open-access papers, as found by Europe PMC text mining. Sharing a sentence is not in itself a finding about the gene and the disease. The quoted sentences say what the papers report.
breast carcinoma (2 papers, 2022 to 2024). "In breast cancer, GALNT14 modulates tumor multidrug resistance and promotes cancer invasion by altering cell proliferation, motility, and EMT gene expression levels, while gene polymorphisms of GALNT16 are strongly associated with cancer susceptibility." (PMID 38244579, 2024). "With respect to the O-GalNAc pathway, we observed alterations in several related glycogenes including the downregulation of GCNT4, GALNT13, GALNT16 and C1GALT1, and upregulation of ST3GAL1, ST6GALNAC4 and GAL3ST2 in Her2+ breast cancer tissue." (PMID 36282863, 2022).
allergic disease (1 paper, 2021). An immune response that occurs following re-exposure to an innocuous antigen, and that requires the presence of existing antibodies against that antigen. "Additionally, several proteins, whose expression could be regulated by these variants, had been previously associated with asthma-related traits and/or allergic diseases (e.g., OLFML3, PCSK3, ZNF180, GALNT16, and KLK14)." (PMID 34442380, 2021).
angina (1 paper, 2019). "These included novel associations of variants at COL5A1 with cerebrovascular disease (P = 4.6 × 10−4), GALNT16 with angina (P = 9.3 × 10−4), MBOAT7 with venous thromboembolism (P = 1.3 × 10−3), GLTPD2 with atherosclerosis (P = 5.3 × 10−4) and SPTLC3 with intracerebral haemorrhage (P = 1.0 × 10−3)." (PMID 31551469, 2019).
glycosylation disorder (1 paper, 2022). "Therefore, we surmise that the downregulation of GALNT16 expression might lead to the occurrence of AF by causing glycosylation disorder." (PMID 35966550, 2022).
liver cancer (1 paper, 2025). An epithelial or non-epithelial malignant neoplasm that arises from the liver. "Specifically, YY1, functioning as a transcription factor, directly amplifies the expression of GALNT16, a glycosyltransferase, thereby enhancing PD‐L1 glycosylation in liver cancer cells and curbing PD‐L1 degradation via the ubiquitination pathway." (PMID 41322030, 2025).
melanoma (1 paper, 2023). A malignant, usually aggressive tumor composed of atypical, neoplastic melanocytes. "And also, MITF and GALNT16 were significantly enriched in the KEGG pathway of melanoma and mucin type O-glycan biosynthesis, respectively." (PMID 36707771, 2023).
pancreatic cancer (1 paper, 2024). "The survival map of the hazard ratio showed that only the expressions of GALNT5, GALNT8, GALNT10, and GALNT16 displayed significant differences in prognosis with pancreatic cancer." (PMID 39433745, 2024).
tumor (6 papers, 2020 to 2025). "The risk score of all tumor samples was counted as follows: Risk score = (0.974* B4GALT3) + (0.418* PYGL) + (0.195* GALNT14) + (−0.413* FUT2) + (−0.886* GALNT16)." (PMID 38244579, 2024). "The results showed that the group with YY1 knockdown combined with anti‐PD‐1 treatment exhibited significant tumor growth inhibition, whereas the GALNT16 overexpression group showed accelerated tumor growth." (PMID 41322030, 2025). "IHC revealed that the YY1 knockdown combined with anti‐PD‐1 treatment group had significantly increased CD8+ T cell infiltration within the tumor, while the GALNT16 overexpression group had reduced CD8+ T cell infiltration." (PMID 41322030, 2025). "Namely, increased B3GNT4 expression was associated with subclonal expansion in at least seven tumor types, while GALNT16 and GALNT17 levels appeared mostly associated with a decrease in intra-tumor heterogeneity across five cancers." (PMID 36009354, 2022). "The expression of Serpine1 in 52 tumor tissues was detected, and the results showed that Serpine1 mRNA level was negatively correlated by circ-GALNT16 expression." (PMID 34452628, 2021). "Circ-GALNT16 expression was negatively correlated with tumor size, tumor stage, and lymph node metastasis." (PMID 34452628, 2021). "In the present study, we investigated the role of a novel circRNA, circ-GALNT16, as a tumor suppressor in CRC." (PMID 34452628, 2021). "The low expression of circ-GALNT16 predicted advanced tumor size, tumor stage, lymphatic metastasis, and poor prognosis." (PMID 34452628, 2021). "To determine the tumor suppression mechanisms of circ-GALNT16 in CRC, we first examined the subcellular location of circ-GALNT16 in CRC cells." (PMID 34452628, 2021). "The results showed that tumors generated from circ-GALNT16-overexpressing cells had less tumor volume and weight than the control group, while circ-GALNT16 depletion had an opposite effect." (PMID 34452628, 2021). "In addition, lower circ-GALNT16 expression in tumor tissues was correlated with shorter OS." (PMID 34452628, 2021). "Subsequently, immunohistochemical staining for YY1, GALNT16, and PD‐L1 was conducted on human HCC consecutive tissue sections, and higher PD‐L1 expression levels were observed in tumor cells within tissues with high expression of YY1 and GALNT16." (PMID 41322030, 2025). "In the tumor cell‐CD8+ T cell coculture system, genetic rescue experiments demonstrated functional restoration of CD8+ T cell activity: knocking down GALNT16 in YY1‐overexpressing tumor cells or overexpressing GALNT16 in YY1‐knockdown cells both reversed YY1‐mediated CD8+ T cell impairment." (PMID 41322030, 2025).
cancer (3 papers, 2022 to 2024). A tumor composed of atypical neoplastic, often pleomorphic cells that invade other tissues. "In contrast, a limited number of genes are predominantly downregulated throughout all cancer types, such as ST6GALNAC6, ST6GALNAC3, GALNT16 and MAN1C1." (PMID 36009354, 2022).
cardiovascular diseases (1 paper, 2025). "Despite GALNT16 being classified as an N‐acetylgalactosaminyltransferase, previous studies have implicated it in protein and lipid metabolism, as well as in AMPK, prolactin, and insulin/IGF signaling pathways, and it may also play a role in lipid metabolism associated with cardiovascular diseases." (PMID 41322030, 2025).
GALNT16 also shares sentences with these, for which no sentence is quoted: asthma (1 paper); atherosclerosis (1); cerebrovascular disease (1); colorectal cancer (1); glioma (1); intracerebral haemorrhage (1); lung adenocarcinoma (1); venous thromboembolism (1).